BCL2 (BCL2 apoptosis regulator)
Diseases named in the same sentence as BCL2 in open-access papers (continued):
Sharing a sentence is not in itself a finding about the gene and the disease.
lung carcinoma (continued). "After all, the protein expression analysis after the MTX, ABL and the optimized MTX-ABL solid dispersion were tested against lung cancer cells for 24 hours using the Enzyme-Linked Immunosorbent Assay (ELISA) to assess the levels of BAX, BCL-2, TGF-β and FR-ɑ." (PMID 39821171, 2025). "Across various radiation dose levels, oridonin heightens lung cancer cells’ radiosensitivity and triggers apoptosis by elevating Bax expression and suppressing Bcl-2." (PMID 40417000, 2025). "In lung cancer, ADCY1 was significantly associated with platinum-based chemotherapy resistance by regulating Bcl-2-mediated apoptosis." (PMID 41550951, 2025). "BEAP inhibits the proliferation of lung-cancer-cell-line A549 by inducing apoptosis through increasing the Bax/Bcl-2 ratio, promoting the release of cytochrome C and activating caspase-3 and caspase-9." (PMID 40507156, 2025). "Artesunate significantly inhibits the growth of lung cancer (A549) cells by interfering with cell cycle progression, reducing the protein expression of Bcl-2 and MMP-9, and increasing the protein expression of Bax." (PMID 40490812, 2025). "Overall, the study demonstrates that peptides from L. squarrosulus mushrooms effectively induce apoptosis in lung cancer cells by decreasing anti-apoptotic Bcl-2 and c-FLIP proteins and increasing the pro-apoptotic protein Bax." (PMID 40142097, 2025). "Further research is needed to fully understand the clinical implications and utility of serum Bcl-2 levels in lung cancer patients." (PMID 40841912, 2025). "Lung cancer models exposed to PTFE implicated MAPK cascade genes and BCL2, consistent with proliferation and apoptosis evasion." (PMID 41378310, 2025). "Nobiletin can induce cellular apoptosis in lung cancer by increasing the level of pro-apoptotic protein Bax, decreasing the level of anti-apoptotic protein Bcl-2 and stopping the cell cycle in G2/M phase." (PMID 39820543, 2025). "In previous studies, synthetic peptides obtained from this species showed proapoptotic activity in lung cancer cell lines, via activation of caspases, inducing a high Bax/Bcl-2 ratio." (PMID 39852534, 2025). "Studies have shown that flavonoid derivatives can regulate the Bax/Bcl-2 ratio and induce apoptosis in lung cancer cells through endogenous pathways." (PMID 40333837, 2025). "Our findings provide additional evidence that MH induces apoptotic cell death by inhibiting Bcl2 and Bcl-XL in drug-sensitive and drug-resistant lung cancer cells in a dose-dependent manner." (PMID 39518013, 2024). "Mechanistically, we demonstrated that in melanoma, breast and lung cancer models Bcl-2 affects Hippo pathway by regulating the level of MST2, a key YAP upstream regulator." (PMID 38755629, 2024). "By exploring the underlying mechanism, we found that circSORBS1 regulates RUFY3 expression directly and indirectly, activates the YWHAE/BAD/BCL2 apoptosis signalling pathway, and ultimately inhibits the development of lung cancer." (PMID 38915053, 2024). "Beyond its effects on T cells, leptin maintains the homeostasis of murine B cells by inducing Bcl-2 and cyclin D1, promoting cell cycle entry and preventing apoptosis, thereby promoting lung cancer cell proliferation." (PMID 38571500, 2024). "It was also involved in regulating the apoptosis of lung cancer cells through the Bcl-2 and p38 MAPK pathways." (PMID 38927108, 2024). "TIPRL depletion in CD133+ cells isolated from lung cancer cells also decreased the expression of Bcl2 and HMG20A." (PMID 39076120, 2024). "This dual regulatory mechanism leads to an increase in RUFY3 protein levels, which ultimately activates the YWHAE/BAD/BCL2 apoptotic signalling pathway and suppresses lung cancer progression." (PMID 38915053, 2024). "In lung cancer, the Bcl-2/BAX/caspase-3 signaling pathway was shown that it can enhance immunogenicity to inhibit the proliferation of lung cancer cells." (PMID 39074253, 2024).
lung carcinoma (continued). "Treatment with FIS led to a significant increase in the expression of Bax and a decrease in the expression of Bcl-2, along with a significant increase in the expression of caspase-3, caspase-9, and cytochrome c in mice with lung cancer." (PMID 38674891, 2024). "In the present study, both hydroethanolic and ether extracts of chia seeds significantly reduced Bcl2 content by about 52 and 56% compared to the lung cancer control." (PMID 39338293, 2024). "Astilbin also augmented the pro-apoptotic effect of cisplatin on human lung cancer cells (A549) via the Bax/Bcl-2/caspase-3 pathway." (PMID 38644901, 2024). "PCR experiments related to mitochondrial pathway apoptosis further confirmed that SA disrupted the Bax/Bcl-2 balance in lung cancer cells, thereby activating mitochondrial pathway-mediated apoptosis through Caspase." (PMID 39430236, 2024). "The data show that MH treatment dose-dependently inhibited both Bcl-2 and Bcl-XL in drug-sensitive (A549 and H1299) and drug-resistant (A549-TR) lung cancer cells." (PMID 39518013, 2024). "Chia alcohol and ether extracts revealed a pro-apoptotic effect via a significant reduction in expression levels of the BCL2 apoptotic gene by about 52 and 56% for chia ether and chia alcohol extracts compared to the control and lung cancer groups (p ≤ 0.05)." (PMID 39338293, 2024). "In our study, we observed that the vanillic acid nanocomposite decreased Bcl-2 and increased Bax expression in lung cancer cells." (PMID 38999050, 2024). "In summary, we elucidated that circSORBS1 activates the RUFY3/YWHAE/BAD/BCL2 signalling pathway through both a sponging mechanism and direct mRNA binding, ultimately inhibiting the development of lung cancer." (PMID 38915053, 2024). "In our study we also found the downregulation of both TEAD2 and FST genes, in lung cancer cells after Bcl-2 silencing." (PMID 38755629, 2024). "Isoflavones (Biochanin A), phytoestrogens found in legumes, have been observed to induce lung cancer cell cycle arrest and apoptosis in A549 and 95D cells by regulating cell cycle-related protein expression and regulating the Bcl-2 and Caspase-3 pathways." (PMID 38628670, 2024). "Piperine was reported to induce cell cycle arrest in the A549 lung cancer cell line at a concentration of 50, 100, and 200 μg/mL by upregulating caspase-3 and caspase-9 cascades and the Bax/Bcl-2 ratio." (PMID 37568796, 2023). "The upregulation of pro-apoptotic (Bax) and downregulation of anti-apoptotic gene (Bcl-2) detected in this study further confirm the occurrence of apoptotic events in A549 lung cancer cells." (PMID 37049823, 2023). "In lung cancer, not only can BCA inhibit epithelial-mesenchymal transition, but it can also suppress the rate of proliferation of lung cancer cells by activating the Bcl-2 and caspase-3 pathways and by regulating the expression of cell cycle-related proteins." (PMID 37111591, 2023). "MiR-146a regulates the main gene TRAF6 and continually Bcl2 via the NF-KB signaling pathway that induces apoptosis in lung cancer." (PMID 36800962, 2023). "In this study, treatment with the GAN/MTX combination downregulated the mRNA expression of survivin and Bcl-2 to 0.55 and 0.43 folds, respectively, as compared to their individual treatment in lung cancer cells." (PMID 37259378, 2023). "Real-time PCR results showed that the expression levels of hTERT and BCL-2 were significantly reduced in lung cancer cell lines treated with MET and SIL compared to single treatments (p< 0.001)." (PMID 37664043, 2023).
lung carcinoma (continued). "In A549 lung cancer cells, chrysin has been shown to increase apoptosis by elevating caspase-3, Bcl-2, and Bax expression." (PMID 37568796, 2023). "The anti‐cancer effects of A. cepa and its main constituent QT are shown by adenocarcinomas parameters inhibition through modulating the expression of B‐cell lymphoma, Bax mRNA, Bcl‐2 mRNA, cell viability and DNA synthesis in lung cancer cells." (PMID 37697969, 2023). "The Bax/Bcl-2 ratio is crucial for regulating apoptosis in lung cancer cells and disrupting mitochondrial homeostasis." (PMID 37959865, 2023). "The findings of this study revealed that the Lentinus squarrosulus mushroom peptide effectively mediated lung cancer cell apoptosis by decreasing the anti-apoptotic Bcl-2 and c-FLIP proteins and raising the pro-apoptotic protein Bax." (PMID 37239989, 2023). "Engagements of TLR7 or TLR8 agonists in lung cancer cells can induce the activation of NF-κB and upregulation of Bcl-2 expression, leading to increases in cell survival and resistance to apoptosis." (PMID 37443143, 2023). "At the molecular level, SCFAs derived from the microbiome inhibit the growth of various cancers, such as colon and lung cancer, by modulating GPCRs, histone hyperacetylation, or through the dysregulation of the expression of BCL-2 and PCNA." (PMID 37564290, 2023). "CIS@AgNPs@PCL fiber-covered stents significantly inhibited lung cancer tissue and enhanced anti-cancer effects by up-regulating caspase-3 and Bax, while down-regulating Bcl-2." (PMID 37719298, 2023). "A similar mechanism of antiproliferative effect in lung cancer cells, i.e., changes in Bcl-2/Bax ratio and activation of caspase-3 and -9, has also been reported for phloretin and HSYA." (PMID 37373500, 2023). "E6-positive lung cancer patients with lower expression of miR-184 and higher expression of Bcl-2 tumors or patients with E6-positive/low-miR-184, low-miR-184/high-Bcl-2, E6-positive/high-Bcl-2 tumors have shown less sensitivity towards cisplatin." (PMID 36778005, 2023). "A good level of caspase-3 and reduced Bcl-2/Bax proportion facilitates apoptosis and lung cancer prevention (Liet al., 2018)." (PMID 38106650, 2023). "The researchers believe these results to be mediated by inhibition of JNK and Bcl-2 expression in A549 lung cancer cell lines." (PMID 37568796, 2023). "The depletion of CHI3L1 increased the CHOP, cleaved caspase 12 levels and Bax/Bcl2 ratio in A549 lung cancer cells." (PMID 37215572, 2023). "Previous research has reported that silencing METTL3 can increase the ratio of Bax/Bcl-2, trigger mitochondrial apoptosis, and prevent the development of lung cancer cells (Wei, Huo & Shi, 2019)." (PMID 38025760, 2023). "In parallel, in the lung, Bcl-2/Bax and lung cancer-related factors CDK1, CDC20, P38α etc were significantly increased in stress+smoke group." (PMID 36417428, 2022). "METTL3 is an important methylase for m6A modification, and it shows important performance in lung cancer, breast cancer, ovarian cancer, gastrointestinal cancer, and leukemia by regulating downstream targets BCL-2, MEC6, and PTEN to inhibit apoptosis." (PMID 35141221, 2022). "Betulinic acid has be demonstrated potent anti-cancer activity against PTX resistant H460 lung cancer cells by regulating BCL-2/BAX." (PMID 35477569, 2022). "As a result, MA treatment potently promoted the apoptosis of several lung cancer cell lines in a dose-dependent manner and downregulated the antiapoptotic protein of BCL2." (PMID 36712673, 2022). "The presence of galangin enhanced DDP-induced apoptosis by inhibiting Bcl-2 in DDP-resistant lung cancer cells." (PMID 36576605, 2022). "Increases Bax expression and decreases Bcl-2 expression, cell cycle arrest at G0/G1 phase in A-549 lung cancer cells." (PMID 35208993, 2022).
lung carcinoma (continued). "Based on these results, we conclude that miR-655-3p acts as a critical suppressor in lung cancer cells proliferation through the downregulation of Bcl-2." (PMID 35473552, 2022). "If the expression of BCL-2 is abnormal in lung cancer, the cells with irreparable genetic changes are prevented from dying and entering the cell cycle." (PMID 36313628, 2022). "Administration of Fisetin resulted in the decrease of antiapoptotic proteins (such as Bcl-2 and Bcl XL), the increase of proapoptotic proteins (such as Bax and bad), and activation of the caspase-3 signaling pathway in lung cancer cells." (PMID 35733630, 2022). "TheC.sappan ethanol extract inhibited cancer cell growth and arrested at G0/G1 phase of cell cycle, inducing apoptosis by increasing BAX/BCL-2 protein ratio in A549 lung cancer cell line." (PMID 36128561, 2022). "Treatment of the A549 lung cancer cell line with the ethyl acetate extract of A.muricata leaves induced apoptosis via the upregulation of Bax and downregulation of Bcl-2 expressions." (PMID 35208993, 2022). "Recent studies have demonstrated that ATO induces apoptosis by reducing Bcl‐2 protein in lung cancer." (PMID 34910369, 2022). "None of the six compounds favored cell proliferation in A549 lung cancer cells or led to the overexpression of oncogenic proteins BCL-2 and BCL-XL." (PMID 35159285, 2022). "Research has revealed that 6 μmol/L of PD activates apoptosis in A549 lung cancer cell lines by impairing Bcl-2 levels and upregulating Bax levels." (PMID 36364001, 2022). "An Ova-mediated cytotoxic effect on A549 lung cancer cells has been indicated by a decrease in Bcl-2 and increase in PUMA, DR5 and Bax protein levels, as well as activation of caspase cascades." (PMID 35163851, 2022). "IGFBP4 overexpression can inhibit tumor proliferation and induce apoptosis by increasing the expression level of the proapoptotic protein BAX and decreasing that of the antiapoptotic protein BCL2 in A549 lung cancer cells." (PMID 36164607, 2022). "BCL-2 is a key inhibitor of the mitochondrial apoptosis pathway, and its high expression levels are associated with poor therapeutic efficacy of PTX in lung cancer patients, and attenuated death in multiple myeloma cells." (PMID 35250564, 2022). "Lung cancer cells treated with doses till 6 μM PD, showed a dose-dependent reduction in Bcl-2 and cyclin D1 levels as well as an increase in Bax, leading to cell cycle arrest at the S phase." (PMID 36364001, 2022). "Emerging evidence reveals that early detection of BCL-2 expression level is of great significance for the treatment of patients with lung cancer." (PMID 36313628, 2022). "Treatment of lung cancer cells with this UA derivative induced apoptosis, as evidenced by the increased cleaved caspase-8 and caspase-7 levels and the decrease in Bcl-2 protein levels." (PMID 36364289, 2022). "ADCY1 can modulate anticancer drugs and regulate cell apoptosis via the Bcl-2-MOM pathway in lung cancer." (PMID 35832555, 2022). "Some studies showed an increase in the expression of the proapoptotic protein Bax and a significant decrease in the expression of the antiapoptotic protein Bcl-2, highlighting the apoptotic effects of ursolic acid on lung cancer cells." (PMID 36364289, 2022). "Montelukast induced down-regulation of Bcl-2, up-regulation of Bcl-2 homologous antagonist/killer, and nuclear translocation of apoptosis-inducing factors in lung cancer cells." (PMID 35463337, 2022). "To further clarify the mechanism of sanguinarine inducing apoptosis in lung cancer cells, we detected the markers of apoptosis, Bax, Bcl-2." (PMID 35949313, 2022). "As competitive inhibitors, antiapoptotic bcl-2 proteins are currently under various clinical and preclinical stages of development for lung cancer treatment." (PMID 36230484, 2022). "In order to further investigate how miR-148a functions in lung cancer pathogenesis, Bcl-2 was studied as one of its molecular targets." (PMID 34181356, 2021).
lung carcinoma (continued). "Consistently, the cell cycle-and apoptosis-related protein expressions of mTOR, STAT3, Bcl-2, and cyclin D1 significantly increased in A549 lung cancer cells after treatment with 100 ng/ml leptin." (PMID 33708630, 2021). "Several studies have indicated that some circRNAs upregulated in lung cancer inhibit cell death, and promote disease progression via upregulating Bcl-2 and/or downregulating Bax expression." (PMID 34295810, 2021). "Tan IIA combined with cyclophosphamide (CTX) can regulate Bcl‐2 and Bax expressions in lung cancer tissues of Lewis mice, inhibit the neovascularization of tumor tissue, enhance immune function, and exert evident anti‐tumor activity." (PMID 33650320, 2021). "Combination of BKA-073 with Bcl-2 inhibitor venetoclax exhibits strong synergy against lung cancer in vivo." (PMID 34373755, 2021). "A different study revealed that FZKA induced lung cancer cell apoptosis involving the STAT3/BCL-2/Caspase-3 pathway." (PMID 33585660, 2021). "Our study showed that Wogonin inhibited the expression of Bcl-2 and promoted the expression of Bad and the activation of caspase-3/cleaved caspase-3, thereby inducing the apoptosis of lung cancer cells." (PMID 34630106, 2021). "As discovered by Sirui Li and colleagues, lung cancer cell radiosensitivity was enhanced by upregulating Bax and downregulating Bcl-2." (PMID 34528498, 2021). "One study showed that targeting anti-apoptotic Bcl-2 protein kills lung cancer cells by activating the mitochondrial cell death program." (PMID 34630106, 2021). "Ultimately, circNOL10 promoted lung cancer cell apoptosis by increasing Bax and caspase-9 expression, and in comparison, decreasing Bcl-2 expression." (PMID 34295810, 2021). "The results of the study showed that SCA had high cytotoxicity to lung cancer cells as well as a strong ability to suppress Bcl-2 expression in lung cancer cells." (PMID 33921340, 2021). "On the other hand, the over-expression of PGM5P4-AS1 significantly inhibited the expression of CyclinD1 (0.37±0.05 vs. 0.93±0.09), MMP-2 (0.41±0.07 vs. 1.22±0.17), Bcl-2 (0.30±0.05 vs. 1.05±0.14), and Bcl-xl (0.37±0.06 vs. 0.91±0.11) in lung cancer cells." (PMID 33315502, 2021). "For example, ABT-263 (Navitoclax), which targets the apoptosis inhibitor Bcl-2, was more effective in lung-cancer cell lines that weakly express AhR." (PMID 33451095, 2021). "The BCL-2-Beclin-1 complex, in turn, inhibits the formation of autophagosomes and, ultimately, autophagy-mediated cell death, promoting lung cancer progression." (PMID 33925645, 2021). "One study demonstrated that treatment with mTOR kinase inhibitors resulted in elevated expression levels of cleaved caspase 3 proteins and dramatically downregulated Bcl-2 levels when mTOR was downregulated in human laryngocarcinoma and lung cancer." (PMID 33925400, 2021). "We performed western blot analysis to evaluate the expressions of key apoptotic factors Bad, Bcl-2, and caspase-3/cleaved caspase-3 in lung cancer cells treated with Wogonin." (PMID 34630106, 2021). "It has been reported that saponin-related compounds induce lung cancer cell apoptosis by increasing the ratio of proapoptotic Bax/antiapoptotic Bcl-2 and decreasing antiapoptotic Mcl-1." (PMID 33750378, 2021). "In the H1650 lung cancer cell line, the pro-apoptotic Caspase-9, Bak, Puma, and Bax protein levels were elevated, while the anti-apoptotic Bcl-2 levels decreased significantly at unchanged Mcl-1 levels, after methyl-donor treatment." (PMID 33808426, 2021).